RAB31 (RAB31, member RAS oncogene family)
Diseases named in the same sentence as RAB31 in open-access papers (continued):
Sharing a sentence is not in itself a finding about the gene and the disease.
colon cancer (5 papers, 2020 to 2024). "Increased RAB31 expression in cancer-associated fibroblasts was suggested to promote colon cancer progression." (PMID 35631574, 2022). "We found that while RAB31 may be expressed in both cancer cells and stromal cells, stromal RAB31 expression is associated with poor prognosis in colon cancer." (PMID 33072555, 2020). "Rab31 was reported to promote the migration of colon cancer cell lines by paracrine HGF, and HGF inhibition abolished the migration of cancer cells mediated by Rab31 expression." (PMID 34975321, 2022). "Overexpression of RAB31 in CAFs promoted colon cancer cell migration in an HGF/MET-dependent manner, suggesting a role for CAF-expressed RAB31 in the migration of colon cancer cells through regulating paracrine secretion of HGF." (PMID 33072555, 2020). "To further investigate the clinical significance of RAB31 expression in colon cancer, we performed immunohistological staining of RAB31 in 98 CRC tumor samples." (PMID 33072555, 2020). "In this study, we aim to characterize the functional and clinical roles of RAB31 in the progression of colon cancer." (PMID 33072555, 2020). "In conclusion, we present RAB31 as an important regulator of HGF secretion in CRC-derived cancer-associated fibroblasts, which plays an important role in the progression of colon cancer through activating HGF/Met signaling in cancer cells." (PMID 33072555, 2020). "RAB31 was expressed in goblet cells of normal colon mucosa as well as in cancer cells in a fraction of colon cancer samples." (PMID 33072555, 2020). "Overexpression of Rab31 in cancer-associated fibroblasts (CAFs) enhances cell migration in an HGF/MET-dependent manner in colon cancer cells, indicating a key role for Rab31-expressed CAF in the colon cancer cell migration by mediating paracrine secretion of HGF." (PMID 38695990, 2024). "RAB31 may be involved in the formation of invadosomes in colon cancer, promoting actin dot formation under an FN-induced signal in EHT, invasion, and pathogen virulence." (PMID 39228892, 2024). "We propose that in colon cancer, increased RAB31 expression in CAFs may contribute to tumor progression by regulating the secretion of HGF in the tumor stroma." (PMID 33072555, 2020). "We demonstrate that increased RAB31 expression in CAFs, a major component of stromal cells, may promote colon cancer progression by increasing HGF secretion which subsequently activates HGF/Met signaling in CRC cells." (PMID 33072555, 2020). "To determine whether elevated expression of RAB31 in CAFs can affect the biological properties of CRC cells, we overexpressed RAB31 in two primary colon cancer-derived CAFs using lentiviral infection." (PMID 33072555, 2020). "Stromal RAB31 expression had worse prognosis in colon cancer." (PMID 33072555, 2020). "In this study, we found that expression of RAB31 in the tumor stroma but not cancer cells of colon cancer predicted poor survival." (PMID 33072555, 2020). "Since RAB31 has never been studied in colon cancer, we validated a commercially available RAB31 antibody using WB and immunocytochemistry and explored the expression and distribution of RAB31 in paraffin-fixed tissue from colon cancer patients." (PMID 33072555, 2020).
colorectal cancer (5 papers, 2020 to 2024). A primary or metastatic malignant neoplasm that affects the colon or rectum. "For example, COL1A1 has been reported to be linked with immune infiltrating cells, and RAB31 is expressed in CAFs, contributing to the malignant potential of colorectal cancer through the secretion of HGF in the tumor stroma." (PMID 38557819, 2024). "RAB31, a protein secreted by CAF, is associated with malignant behavior in breast, hepatocellular, gastric, and colorectal cancers." (PMID 37207166, 2023). "In our previous study, we found that Ras-related protein Rab-31 (RAB31) expression was increased in late-stage colorectal cancer (CRC)." (PMID 33072555, 2020). "Therefore, it would be interesting to investigate the functional role of RAB31 in other cell types such as immune cells since CMS1 (immune infiltration type) colorectal cancer also express high levels of RAB31." (PMID 33072555, 2020). "The PPI networks indicate the RAB31, COL1A1, COL1A2, COL3A1, COL11A1, and VCAN as the most important protein network that likely to be connected and show betweenness among themselves to significantly promote the prognosis of colorectal cancer." (PMID 33597969, 2021).
hepatocellular carcinoma (5 papers, 2018 to 2024). A malignant tumor that arises from hepatocytes. "Additionally, elevated Rab31 expression was associated with poor prognosis in hepatocellular carcinoma through inhibition of apoptosis via the Bcl-2/Bax pathway." (PMID 31083279, 2019). "For example, Rab31 expression in hepatocellular carcinoma tissues is remarkably higher than that in adjacent liver tissues, and Rab31 is a novel prognosis biomarker in patients with hepatocellular carcinoma." (PMID 36781842, 2023). "Specifically, RAB31 might promote hepatocellular carcinoma progression by inhibiting cell apoptosis induced by the PI3K/AKT/Bcl‐2/BAX pathway." (PMID 29957874, 2018).
glioma (4 papers, 2022 to 2024). A benign or malignant brain and spinal cord tumor that arises from glial cells (astrocytes, oligodendrocytes, ependymal cells). "Here, we found the expression of RAB31 in glioma vascular endothelial cells and normal cerebral vascular endothelial cells is heterogeneous, and the effect of RAB31 on glioma angiogenesis needs to be further studied." (PMID 37953466, 2024). "Here, we identified an EV export mechanism for MYO1C that promotes glioma cell invasion and is dependent on RAB31 in GhECs." (PMID 37953466, 2024). "In general, the activation of SPRY4, ERRFI1, and RAB31 can be used for developing new approaches to glioma therapy." (PMID 36231068, 2022). "In addition, the knockdown of RAB31 significantly attenuated the promotion of glioma cell invasion by GhEC‐EVs." (PMID 37953466, 2024). "Finally, we identified an EV export mechanism for MYO1C that promotes glioma cell invasion and is dependent on RAB31 in GhECs." (PMID 37953466, 2024). "Furthermore, a recent study reports that RAB31 silencing attenuates glioma invasion, process mediated by EVs from glioma-derived endothelial cells." (PMID 38347462, 2024). "The identification of the SPRY4, ERRFI1, and RAB31 as genes whose natural activation provides the inverse regulation of the processes of neurosphere formation can be used for creating new strategies of suppressing the invasion and progression of gliomas." (PMID 36231068, 2022). "Knockdown of RAB31 reduces enrichment of MYO1C in extracellular vesicles, thereby attenuating promotion of glioma cell invasion by GhEC‐EVs." (PMID 37953466, 2024). "In summary, our data indicate that the knockdown of RAB31 can reduce enrichment of MYO1C in extracellular vesicles, thereby attenuating the promotion of glioma cell invasion by GhEC‐EVs." (PMID 37953466, 2024). "In summary, our data illustrate that the knockdown of RAB31 can reduce the enrichment of MYO1C in extracellular vesicles, thereby attenuating the promotion of glioma cell invasion by GhEC‐EVs." (PMID 37953466, 2024). "We also detected that the upregulation of SPRY4, ERRFI1 and RAB31 provides a condition for feedback regulations of FGF and EGF signaling as well as can be applied in glioma therapy." (PMID 36231068, 2022). "Furthermore, we found three EGFR and FGFR signaling feedback regulators common to all analyzed gliomas—SPRY4, ERRFI1, and RAB31—which can be used for creating new therapeutic strategies of suppressing the invasion and progression of gliomas." (PMID 36231068, 2022). "Interestingly, we found three commonalities for all analyzed glioma feedback regulators of the EGFR and FGFR signaling pathways: SPRY4, ERRFI1 and RAB31." (PMID 36231068, 2022).
lung carcinoma (4 papers, 2019 to 2025). "The degree of correction between the expression level of RAB31 and gene expression profiles suggestive of immune infiltration were weak to strong (r = 0.128–0.452) in breast and lung cancers, and strong to very strong (r = 0.38–0.70) in colorectal, liver, stomach, and prostate cancers." (PMID 34359748, 2021). "It has been reported that, upon stabilisation by Rab31 or SNHG19, ERK3 promotes EMT markers in cervical and lung cancers." (PMID 40936697, 2025).
stomach adenocarcinoma (3 papers, 2022 to 2023). "Additionally, Rab31 mediates cisplatin resistance and metastasis in stomach adenocarcinoma via epithelial-mesenchymal transition pathway." (PMID 37207166, 2023).
atherosclerosis (2 papers, 2022 to 2024). A disease characterized by the build-up of fatty material and calcium deposition in the arterial wall resulting in partial or complete occlusion of the arterial lumen. "Moreover, we identified several novel genes not previously linked to SMCs in atherosclerosis, such as Anxa4, Cd276, inter-alpha-trypsin inhibitor-4 (Itih4), Myof, Pcdh11x, Rab31, Serpinb6b, Slc35e4, Slc8a3, and Spink5." (PMID 38289873, 2024). "The gene list included well-known atherosclerosis-associated genes Serpina3,42Cemip,43Thbs1,44Lum,45 and Spp146,47 but also novel genes without previous association to SMC function in atherosclerosis, such as Anxa4, Cd276, Itih4, Myof, Pcdh11x, Rab31, Serpinb6b, Slc35e4, Slc8a3, and Spink5." (PMID 38289873, 2024).
melanoma (2 papers, 2023). A malignant, usually aggressive tumor composed of atypical, neoplastic melanocytes. "We found that miR-195-5p overexpression in BRAF-mutated melanoma cells causes an increase in the expression levels of some EVs biogenesis-related genes like RAB27b, RAB31, and/or FLOT2, which was accompanied by a consequent increase in CD63 and CD9 positive EVs secretion." (PMID 37174717, 2023). "Fifthly, we identified ‘4‐genes risk prediction model’ (RNF11, NUDT21, RAB31, and ARID4B) and the ‘glycolysis‐prognosis‐10‐gene set’ that each confers independent prognostic significance for melanoma." (PMID 37356089, 2023). "Univariate COX analysis revealed that RAB31, NUDT21, and ARID4B genes were tumor suppressive in clinical melanoma samples (P < 0.1)." (PMID 37356089, 2023).
ovarian carcinoma (2 papers, 2022 to 2025). A malignant neoplasm originating from the surface ovarian epithelium. "RMRP accelerates esophageal squamous cell carcinoma through the miR-580-3p/ATP13A3 axis and promotes ovarian cancer invasion via RAB31-dependent MMP secretion." (PMID 40565315, 2025). "RMRP promotes ovarian cancer invasion via RAB31-dependent MMP secretion." (PMID 40565315, 2025).
prostate carcinoma (2 papers, 2021 to 2025). A carcinoma that arises from epithelial cells of the prostate gland. "RAB31 mRNA expression level was decreased in cancer group compared to that in normal group, but after hypoxic treatment, the mRNA level of RAB31 increased in some prostate cancer cell lines while decreased in others." (PMID 41214670, 2025).
bladder cancer (1 paper, 2012). "The possible role of the deregulation of intracellular trafficking of surface receptors in bladder cancer progression is supported by the finding that RAB31 is up-regulated." (PMID 22724020, 2012).
Bowen’s disease (1 paper, 2022). "Our study confirmed that up-regulation of RAB31 in CSCC relative to Bowen disease and RAB31 may play a crucial role in CSCC invasion, metastasis process." (PMID 36085041, 2022). "And next, among 20 proteins, 8 proteins (TNC, FSCN1, SERPINB1, ACTN1, RAB31, COL3A1, COL1A1 and CD36) expressed levels showed significant differences between CSCC and Bowen disease." (PMID 36085041, 2022). "Besides, the proteins of TNC, FSCN1, SERPINB1, ACTN1 and RAB31 in CSCC were significantly up-regulated, while COL3A1, COL1A1 and CD36 were significantly down-regulated relative to Bowen disease in proteomics results." (PMID 36085041, 2022).
breast tumors (1 paper, 2012). "The present results demonstrate that Rab31 expression is significantly higher in breast tumors as compared to normal breast tissue." (PMID 22792175, 2012).
colorectal tumor (1 paper, 2020). "Next, we analyzed the expression of RAB31 in colorectal tumor samples based on the consensus molecular subtypes (CMS) classification." (PMID 33072555, 2020).
epidermoid carcinoma (1 paper, 2024). "This is in concordance with the role of Rab22B (also known as Rab31) in epidermoid carcinoma cells, suggesting the convergent function of Rab22 subfamily." (PMID 39206796, 2024).
invasive breast carcinoma (1 paper, 2019). A carcinoma that infiltrates the breast parenchyma. "Another fusion transcript of Rab31 was detected in a patient with invasive breast carcinoma and was originated by the fusion form of DLGAP1-Rab31." (PMID 31083279, 2019).
liver fibrosis (1 paper, 2024). "Additionally, glycolysis in HSCs is elevated during liver fibrosis, leading to increased expression of the EV-related protein RAB31, which further enhances EV release and promotes the expression of fibrosis-related genes in recipient HSCs, thereby amplifying liver fibrosis." (PMID 39767572, 2024).
lung adenocarcinoma (1 paper, 2019). A carcinoma that arises from the lung and is characterized by the presence of malignant glandular epithelial cells. "Here, we describe the identification of a fusion gene comprising part of the coding regions of Rab31 and VAMP-associated protein A (VAPA) through RNA-sequencing in patients with lung adenocarcinoma." (PMID 31083279, 2019). "A fusion transcript of Rab31 and VAPA was detected from RNA-sequencing data of a Korean patient with lung adenocarcinoma." (PMID 31083279, 2019).
oral squamous cell carcinoma (1 paper, 2023). "Recently, Rab31 was found to be involved in EMT in oral squamous cell carcinoma." (PMID 36781842, 2023).
osteosarcoma (1 paper, 2022). A usually aggressive malignant bone-forming mesenchymal neoplasm, predominantly affecting adolescents and young adults. "Studies have shown that the Hedgehog signaling pathway is upregulated in osteosarcoma 25 and that Rab31 knockdown reduces the invasion capacity of osteosarcoma cells via inhibition of the Hedgehog signaling pathway." (PMID 34975321, 2022). "Additionally, Rab31 promotes the proliferation and metastasis of osteosarcoma cells." (PMID 34975321, 2022).
Sepsis (1 paper, 2022). Sepsis is defined as life-threatening organ dysfunction caused by a dysregulated host response to infection. "Another study using GEO data identified SH3GLB1, PGS1, and RAB31 as diagnostic markers for pediatric sepsis, a possible risk factor for KD pathogenesis." (PMID 36042431, 2022).
triple-negative breast carcinoma (1 paper, 2025). An invasive breast carcinoma which is negative for expression of estrogen receptor (ER), progesterone receptor (PR), and human epidermal growth factor receptor 2 (HER2). "Our results revealed significantly higher expression levels of Rab31 in the triple-negative breast cancer cells compared to the breast epithelial cells, with statistically significant differences." (PMID 41463174, 2025). "This study investigates the novel mechanism by which Connexin 43 (Cx43) promotes triple-negative breast cancer (TNBC) progression by regulating Rab31-mediated autophagy." (PMID 41463174, 2025). "This suggests Rab31 plays a key role in the autophagy signaling pathway and promotes triple-negative breast cancer progression." (PMID 41463174, 2025). "Collectively, these experiments indicate that Rab31 may promote the progression of triple-negative breast cancer by influencing key proteins in the autophagy pathway." (PMID 41463174, 2025). "Consequently, we hypothesize that Cx43 may interact with Rab31 to contribute to the progression of triple-negative breast cancer through autophagy." (PMID 41463174, 2025). "Consequently, we evaluated the expression levels of Rab31 using qPCR and Western blotting in breast epithelial cells (MCF-10A) and two triple-negative breast cancer cell lines (MDA-MB-231 and BT-549)." (PMID 41463174, 2025). "To determine if Rab31 is differentially expressed in triple-negative breast cancer, we used qPCR and Western blot analyses to detect its mRNA and protein levels in normal epithelial cells (MCF10A) and triple-negative breast cancer cell lines (MDA-MB-231 and BT-549)." (PMID 41463174, 2025).
uveal melanoma (1 paper, 2017). A melanoma derived from melanocytes of the uveal tract. "Interestingly, unmethylation of the proto-oncogen RAB31 was a predictor of metastasis risk in uveal melanoma." (PMID 28924151, 2017). "The Kaplan-Meier survival analysis of 67 primary uveal melanoma samples demonstrated that RAB31 unmethylation is a predictor of poor outcome in uveal melanoma." (PMID 28924151, 2017). "Specifically, unmethylation of the RAB31 promoter is a predictor of poor outcome in uveal melanoma." (PMID 28924151, 2017). "Only one gene from this panel, RAB31, a member of the RAS oncogene family, showed differential methylation between normal uvea and uveal melanoma, although the methylation level in individual cancer patients was highly variable." (PMID 28924151, 2017).